PRLR (prolactin receptor)
Diseases named in the same sentence as PRLR in open-access papers (continued):
Sharing a sentence is not in itself a finding about the gene and the disease.
psoriasis (1 paper, 2013). An autoimmune condition characterized by red, well-delineated plaques with silvery scales that are usually on the extensor surfaces and scalp. "The down-regulation of follicular PRLR expression by TNFα is also intriguing in view of the importance of TNFα in both inflammatory dermatoses such as psoriasis and hair growth." (PMID 23626671, 2013). "Since pituitary PRL secretion may be regulated by IFNγ and TNFα, albeit in rodent studies, and since these cytokines and PRL have been implicated in the pathogenesis of psoriasis, we also examined whether these prototypic pro-inflammatory cytokines influence PRL and PRLR expression in the HF." (PMID 23626671, 2013). "In follow-up studies, the epidermal regulation of PRL and/or PRLR protein expression by TNF deserves to be characterized, since increased TNFα and PRL levels in psoriasis may both result in a decrease in PRLR expression." (PMID 23626671, 2013).
renal carcinoma (1 paper, 2021). A carcinoma arising from the epithelium of the renal parenchyma or the renal pelvis. "The study also indicated a negative feedback relationship between PRLR and PRL in renal cancer." (PMID 34539753, 2021).
squamous intraepithelial lesions (1 paper, 2021). "PRLR was also increased in patients with low and high squamous intraepithelial lesions and CC, especially in this last group, by immunohistochemistry assays, concluding that high levels of PRLR in the CC patients correlated to the degree malignancy of the cervical tissues." (PMID 34745013, 2021).
thymic atrophy (1 paper, 2013). "Considering theimmunomodulatory role of PRL upon the effects caused by GC, we investigated if intrathymiccross-talk between GC and PRL receptors (GR and PRLR, respectively) might influence T.cruzi-induced thymic atrophy." (PMID 24324845, 2013).
tumor (97 papers, 2003 to 2025). "Elevated serum prolactin levels and increased expression of the long form prolactin receptor (LFPRLR) on tumor parenchyma are associated with higher risks of cancer progression." (PMID 34375938, 2021). "Among these, PRL/PRLR was observed to have a specific association with tumor fibrosis, and PRLR was confirmed by IHC (n = 68, rho = −0.281, p = 0.020)." (PMID 34539753, 2021). "Next, we examined the effects of loss of PRLR expression on tumor development in vivo in HER2-E SKBR-3 CDX mouse models." (PMID 33446633, 2021). "These associations between prolactinomas and the two ICD PRLR rare variants (Glu376Gln and Asn492Ile) remained significant in separate sub-analyses of leucocyte and tumor DNA from 35 and 15 patients, respectively." (PMID 30445560, 2019). "On the other hand, loss of PR/PRLR expression in primary tumors is associated with a less differentiated more invasive phenotype and worse prognosis, suggesting a tumor suppressive role for PR/PRLR during later stages of tumor progression." (PMID 27248476, 2016). "Another mechanism potentially participating in local amplification of PRLR signaling in tumor contexts has recently emerged, and involves gain-of-function of PRLR variants." (PMID 24148306, 2013). "We here investigated the prolactin receptor (PRLr) which is associated with tumours of the breast and other organs." (PMID 22606260, 2012). "Similar expression patterns with cytoplasmic granular and/or membranous location have been reported for other tumour types, where PRLr expression has also been associated with patient outcome." (PMID 22606260, 2012). "Our study shows for the first time that in a large cohort of patients, PRLR expression in tumour tissues is significantly associated with a decreased survival in SCCHN patients." (PMID 21505459, 2011). "Another possible tumor-associated antigen for TNBC therapy is prolactin receptor (PRLR)." (PMID 33670942, 2021). "We further measured the protein chips of 640 cytokines in ccRCC specimens and found that several cytokines, including prolactin (PRL), were associated with the degree of fibrosis in the tumor, as confirmed by the prolactin receptor (PRLR) immunohistochemical method." (PMID 34539753, 2021). "In a phase I clinical trial, the monoclonal antibody LFA102, a humanized neutralizing monoclonal antibody directed against the extracellular domain of PRLR, was tested in patients with advanced BC, which had previously caused tumor shrinkage in an in vivo model of BC." (PMID 34745013, 2021). "Interestingly, a statistically significant inverse correlation was observed between the PRLR gene expression and calcium levels, suggesting either a relationship to a subgroup of tumours and/or a causal change of calcium set point in the tumour." (PMID 22606260, 2012). "Deficiencies in PRLR signaling due to PRLR activity alterations or wrong intracellular pathway connectivity, crosstalk, or co-regulation exerted by other factors, such as hypothalamic or paracrine mechanisms, can lead to pituitary hyperplasia and eventual tumor development." (PMID 36714572, 2022). "utilized an antagonist peptide of PRL, G129R, which blocked the tumoral PRL/PRLR axis in orthotopic mouse models of human OCs, causing inhibition of tumor growth; they reported a synergistic effect of G129R with paclitaxel, which resulted in >90% lower tumor weights compared to controls." (PMID 34745013, 2021). "Thus, there might be an association between low ESR1, PGR and PRLR expression and the associated prognosis of the tumor." (PMID 27649560, 2016). "Analysis of multiple human cancers reveals distinct expression patterns of cyclooxygenase-2 (COX-2), prolactin, and PRLR in tumor and stromal cells." (PMID 41583437, 2025). "This subtype exhibits significant differences from primary site tumor cells, with high expression of the prolactin receptor (PRLR)." (PMID 41583437, 2025).
tumor (continued). "We evaluated tumor characteristics by PRLR, pSTAT5, and JAK2 expression among premenopausal and postmenopausal women." (PMID 36882838, 2023). "Further, we were able to evaluate nuclear and cytoplasmic tumor cell compartments for staining of PRLR and pSTAT5 to evaluate differences by cellular location of marker expression." (PMID 36882838, 2023). "The increased concentration of prolactin subsequently induced the expression of PRLR in neighboring tumor cells, thereby promoting early metastasis in prostate cancer." (PMID 37746302, 2023). "This subtype displayed notable differences compared to tumor cells found at primary sites and exhibited a high expression of prolactin receptor (Prlr)." (PMID 37746302, 2023). "Overall, premenopausal women had slightly more tumor differences (e.g., tumor grade and tumor size) by PRLR, pSTAT5, and pJAK2 expression than postmenopausal women; however, the sample size was limited." (PMID 36882838, 2023). "PRL-induced Stat5 activation is associated to high-grade prostate tumors and aggressiveness, and PRLR inhibition reduced tumor burden." (PMID 37208719, 2023). "We observed some differences in tumor characteristics (i.e., ductal/lobular, lymph node involvement, tumor grade, and tumor size) by PRLR, pSTAT5 and pJAK2 expression and menopausal status." (PMID 36882838, 2023). "As for PRLR, prolactin (PRL) has been traditionally associated with lactation and fertility, but recently it has been reported to promote tumor cell proliferation, angiogenesis, and chemoresistance." (PMID 36836422, 2023). "All 10 DEGs found in the patients who lived in Sao Paulo city compared to the MRSP were associated with cell proliferation and tumor development (BMP4, CTNNBP1, DISP1, DVL1, ERBB4, PRLR, WNT5b, LEF1, PGR, and PTEN)." (PMID 36768749, 2023). "Penfluridol effectively inhibited PRLR signaling and maintained potent anti-tumor activity in multiple mouse models of PDAC." (PMID 36714582, 2022). "Preclinical data, epidemiological studies, and patient tumor tissues analyses strongly support the contribution of PRL/PRLR to breast tumorigenesis and cancer progression." (PMID 36187116, 2022). "In one scenario, alteration of PRLR-related actions locally at the pituitary level, either initiating or contributing to tumor development." (PMID 36714572, 2022). "In contrast, Shemanko and her colleagues found that higher tumor PRLR protein levels correlated with a shorter time to bone metastasis, consistent with experimental PRL-induced osteoclast differentiation." (PMID 35784527, 2022). "Regarding the findings in GBM tumor tissue, a high expression of prolactin and the prolactin receptor has been shown to have a detrimental effect on survival in males only." (PMID 35159938, 2022). "In the context of cancer, several groups have shown anti-tumor activity and suppression of PRLR signaling following treatment with the Δ1-9-G129R-hPRL antagonist." (PMID 36714582, 2022). "There is a complex interplay between PRLR and estrogen receptor (ERα), and there is an important role for the tumor microenvironment." (PMID 36187116, 2022). "While these strategies have shown antagonization of PRLR in pre-clinical studies, poor bioavailability and stability can result in less durable responses, leading to tumor progression." (PMID 36714582, 2022). "At higher doses of 3 mg/kg, PRLR-DbsAb substantially suppressed tumor growth, as both tumor volume and weight were impaired compared to control, and further increase survival of mice." (PMID 36714582, 2022). "PRLR-DbsAb treatment significantly inhibited tumor growth at 0.33 mg/kg, which was comparable to PRLR monoclonal antibody alone." (PMID 36714582, 2022). "We further investigated the tumor-suppressive role of PRLR-SF in vivo using subcutaneous and orthotopic transplantation." (PMID 33664869, 2021).
tumor (continued). "Second, this study combined protein microarray analysis to look for differentially expressed genes and found a significant correlation between PRL/PRLR and fibrosis in tumor tissues." (PMID 34539753, 2021). "Significantly, ABBV-176 demonstrated anti-tumor efficacy against low PRLR expressing BrCa PDX models." (PMID 34107902, 2021). "The role of PRLR in OC seems to be essential for maintaining the tumoral status: PRLR deletion in OVCAR3 cells leads to blockage of tumor formation." (PMID 34745013, 2021). "The survival plots depict lower progression-free survival with higher expression of PRLR in high grade tumor (Hazard ratio = 1.47, P-value <0.05) and low grade tumor (Hazard ratio = 1.68, P-value <0.05) as illustrated in." (PMID 34358244, 2021). "The strikingly rapid and robust tumor collapse caused by SMI-6, raises the possibility that in addition to blocking tumor PRLR, SMI-6 is converted in vivo to a more active metabolite." (PMID 34071395, 2021). "•Knockdown of the long form prolactin receptor reduces Treg recruitment to tumors by reducing tumor parenchymal production of CCL-17." (PMID 34375938, 2021). "To explore how PRLR-SF inhibits tumor growth, we performed genome-wide cDNA microarray analyses of control AsPC-1 cells (AsPC-1-Ctrl cells) and cells that overexpress PRLR-SF (AsPC-1-PRLR-SF cells)." (PMID 33664869, 2021). "COX-2, prolactin, and prolactin receptor show consistent differential expression in tumor and stromal compartments across several human cancers." (PMID 33634114, 2021). "We analyzed the levels of PRLR mRNA in tumor tissues using the TCGA database and found a correlation between high levels of PRLR mRNA and longer survival times for patients with PDAC." (PMID 33664869, 2021). "Altogether, these results reveal that PRLR-SF overexpression reduces the proliferation and colony formation of PDAC cells and reduces their growth as xenograft tumors in mice, suggesting a tumor-suppressive role of PRLR-SF." (PMID 33664869, 2021). "We used the NOD/SCID mouse model to assess the PRLR-DbsAb activity in vivo due to its unique advantage in evaluating candidate drug in human tumor transplanted animal systems." (PMID 32398042, 2020). "Due to the more recent demonstration of PRL production outside the pituitary gland, attempts have been made to modulate tumor production of PRL by using PRLR antagonists (PRLRA)." (PMID 32121009, 2020). "Immune cells were found throughout the denatured and necrotic tumor tissue in a 3 mg/kg PRLR-DbsAb treated mice." (PMID 32398042, 2020). "In vivo results illustrated that 0.33 mg/kg PRLR-DbsAb had the comparable anti-tumor activity with PRLR mAb at a dosage of 3 mg/kg." (PMID 32398042, 2020). "In this study, a bispecific antibody targeting both tumor antigen PRLR and T cell surface CD3 antigen (PRLR-DbsAb) was constructed by split intein mediated protein transsplicing (BAPTS) system for the first time." (PMID 32398042, 2020). "We found that the expression of ERα and PRLR was decreased in the second surgery tumor tissues after oral administration of Bromocriptine." (PMID 33173437, 2020). "Compared with placebo group, PRLR mAb at a dosage of 3 mg/kg exhibited a slight inhibition of tumor growth, which was comparable to PRLR-DbsAb with a low dosage of 0.33 mg/kg." (PMID 32398042, 2020). "PRLR mAb or PRLR-DbsAb was intraperitoneally administrated once per week starting the second day after tumor implantation." (PMID 32398042, 2020). "Our analysis of transcriptomic data from GBM samples indicates that virtually all tumours express PRLR mRNA." (PMID 31862900, 2019). "Subsequently, the co-expression levels between PRLR and TGFβ receptors were evaluated in cases representing different stages of tumor progression." (PMID 30987013, 2019). "In fact, analysis of transcriptomic data indicated that PRLR expression is positively correlated with the levels of MMP-2 expression in tumour samples from GBM patients." (PMID 31862900, 2019).
tumor (continued). "When analysing the expression of prolactin receptor (PRLR), higher levels in the primary tumour are seen associated with a shorter time to BM." (PMID 28194227, 2017). "Our data provide a mechanism for how tumor environments can shift PRLR signals away from physiological STAT5, and subsequent positive prognostic outcomes, to the poorer outcomes of increased signals through focal adhesions." (PMID 27344177, 2016). "From their findings, PRL interacted with short form PRLR to constrain tumor promoting liver inflammation." (PMID 27102295, 2016). "A combined exposure of the angiogenic inhibitors endostatin and tumastatin up-regulates Prl receptors (PrlR) in GBM cells through direct action of integrin-targeting factors on tumor cells." (PMID 27788487, 2016). "In 50% of these patients, PrlR was detected at high-grade (as defined >25% positive cells) in the tumours." (PMID 27788487, 2016). "ATP1B1, GPC3, KCNIP3, and PRLR transcript levels in tumor tissues were significantly lower in PTCs than in NT, whereas LCN2, LGALS1 and SCD1 expression was upregulated in PTC compared with NT." (PMID 27249794, 2016). "Tumor cells can also express prolactin receptor, indicating the use of prolactin in the genesis of this neoplasm." (PMID 25789031, 2015). "Beside the already mentioned pro-proliferative activity of PRLR in diverse tumor entities, several groups have reported about a PRLR/PRL-mediated inhibition of apoptosis especially in response to chemotherapy." (PMID 24257371, 2013). "The same tumor material used for microarray analyses was histologically analysed for the expression of PRLR." (PMID 24257371, 2013). "In fact, T47D xenotransplant tumor regions expressing high GLUT1 were resistant to exogenous prolactin despite retaining prolactin receptor and Stat5 expression." (PMID 24004716, 2013). "Cytoplasmic expression of PRLr was observed in virtually all tumour cells, in 34/36 analysed cases, and 16 tumours showed immunostaining of cytoplasmic granulae in varying subsets of the cells." (PMID 22606260, 2012). "The association to clinical characteristics in parathyroid and other tumours would suggest a functional PRLr." (PMID 22606260, 2012). "N-glycosylated PRLr was mainly observed as a product of 60/70 kDa in size, which was detected in all tumours analysed." (PMID 22606260, 2012). "Expression of PRLR was observed in 89 primary tumours with 8 (9%) cases showing focal, 16 (18%) moderate and 65 (73%) extensive immunoreactivity, respectively." (PMID 21505459, 2011). "Multivariate COX regression analysis confirmed high levels of PRLR expression (>25% of tumour cells) to be an independent prognostic factor with respect to overall survival (HR=3.70, 95% CI: 1.14–12.01; P=0.029) and disease-free survival (P=0.017)." (PMID 21505459, 2011). "Disease-free survival after 5 years was documented in 36 out of 81 (44%) patients with tumours with high PRLR expression and 7 out of 8 (87%) patients with tumours showing low PRLR expression (P=0.017, log-rank test)." (PMID 21505459, 2011). "We found that >90% of primary tumours included in our study were positive for PRLR, but its expression was variable, ranging from very low to high." (PMID 21505459, 2011). "In the second study, PRLR measured by a ligand binding assay and by PRLR mRNA using RT–PCR were detectable in 8 out of 24 (33%) and 41 out of 50 (82%) of tumour samples, respectively." (PMID 21505459, 2011). "The PRLR expression was initially assessed in SCCHN cell lines (n=8) established from primary tumours and the corresponding metastases from four patients." (PMID 21505459, 2011). "Human GH can also activate PRLR, which potentially exerts additional pro-tumor effects." (PMID 41515995, 2025). "Previous studies have indicated that the association between PRLR and inflammatory response may be a key mechanism through which PRLR contributes to tumor progression." (PMID 40978029, 2025).